LGR5 (leucine rich repeat containing G protein-coupled receptor 5)
Diseases named in the same sentence as LGR5 in open-access papers (continued):
Sharing a sentence is not in itself a finding about the gene and the disease.
metastatic tumors (9 papers, 2015 to 2024). "Residual HRCs occult in mouse livers after primary CRC surgery gave rise to multiple cell types over time, including Lgr5+ stemlike tumor cells, and caused overt metastatic disease." (PMID 36352230, 2022). "Taken together, these findings suggest that Lgr5 may be a potential target for patients with aggressive and metastatic tumors, as well as a prognostic marker for ESCC." (PMID 28404917, 2017). "Taken together, these findings suggest that LGR5 may be both a prognostic marker and a potential target for patients with aggressive and metastatic tumors." (PMID 26416247, 2015). "For example, larger samples should be analyzed to detect Lgr5 and CXCR4 expression not only in primary CRCs, but also in metastatic tumors." (PMID 27835894, 2016). "More importantly, treatment with Diphtheria toxin (DT) before surgical removal of the primary CRC effectively eliminated Lgr5+ cells, yet it did not prevent disease relapse and mice developed overt liver metastatic disease." (PMID 36352230, 2022).
cyst (8 papers, 2013 to 2023). A sac-like closed membranous structure that may be empty or contain fluid or amorphous material. "Interestingly, the Hmga1 organoids generated from purified Lgr5+ ISCs adopt a cyst-like, spherical structure similar to the morphology observed in organoids treated with Wnt or engineered to overexpress Ascl2, a transcription factor important in maintaining stem cell identity in ISCs7." (PMID 28452345, 2017). "Furthermore, we observed some Lgr5+ cells and progeny cells higher up at the bottom of the hair follicle remnant (just below sebaceous glands), and in the string of cells running down to the cyst." (PMID 27409834, 2016). "In vitro, duct fragments from mouse pancreas initiate Lgr5 expression in RSPO1-based cultures, and develop into budding cyst-like structures (organoids) that expand five-fold weekly for >40 weeks." (PMID 24045232, 2013). "To determine whether Hmga1 organoids remained in a cyst-like structure because they were comprised predominantly of undifferentiated Lgr5+ stem cells, we stained for the ISC marker, Lgr5-GFP+." (PMID 28452345, 2017).
endometriosis (8 papers, 2018 to 2025). The growth of functional endometrial tissue in anatomic sites outside the uterine body. "The transcriptionally closest epithelial cells were glandular secretory, SOX9+ LGR5+ epithelial cells and ciliated in the eutopic endometrium of donors with endometriosis." (PMID 39149248, 2024). "A recent study discovered leucine‐rich repeat sequence‐containing G protein‐coupled receptor 5 (LGR5) cells in the endometrial tissue of patients with endometriosis." (PMID 37632165, 2023). "Surprisingly, LGR5 was also detected in the endometrial tissue of women with endometriosis, especially in intestinal DIE." (PMID 37632165, 2023). "According to the previous works, a significant increase in the LGR5 gene expression can play an important role in the infertility of women who suffer from endometriosis." (PMID 33718760, 2021). "In the context of endometrial epithelial progenitor/stem cells, it will be important in future studies to determine if the other suggested epithelial progenitor cells expressing N-cadherin, or LGR5 play a role in the pathogenesis of endometriosis." (PMID 30496412, 2019). "This expression pattern was also observed by our group in LGR5+ cells from eutopic endometrium from women with endometriosis." (PMID 30577586, 2018). "In the present work, we also assessed differences between percentages of LGR5+ cells in eutopic endometrium in healthy women and women with endometriosis in both menstrual phases." (PMID 30577586, 2018). "Only four studies on LGR5 have been performed in healthy human eutopic endometrium and, to our knowledge, this is only the second work to explore LGR5 in the eutopic endometrium of women with endometriosis—the first study was published by our group." (PMID 30577586, 2018). "Our results open a new window to study LGR5+ cells in ectopic lesions and discover their role in the pathophysiology and aggressiveness of endometriosis." (PMID 30577586, 2018). "Interestingly, CCC cancer cells displayed transcriptional similarity to glandular secretory, ciliated, and SOX9+ LGR5+ epithelial found in endometriosis conditions." (PMID 39149248, 2024). "However, when comparing LGR5 expression in the eutopic endometrium from healthy patients and endometriosis patients, we observed a statistically significant increase in LGR5 expression in proliferative, secretory, and menstrual phases in healthy women." (PMID 30577586, 2018). "However, we did observe a significant increase in LGR5 in healthy endometrium as measured by immunofluorescence in all phases of the menstrual cycle compared to women with endometriosis." (PMID 30577586, 2018). "We sought to determine whether LGR5+ cells vary across the menstrual cycle in women with endometriosis and whether there are implications for LGR5 in the aggressiveness of endometriosis and reproductive outcomes." (PMID 30577586, 2018). "We assessed whether LGR5+ cells vary throughout the menstrual cycle, along with the percentage of LGR5+ cells in ectopic versus eutopic endometrium, as these cells may have implications for reproductive outcomes in endometriosis." (PMID 30577586, 2018). "We also observed higher levels of LGR5+ cells in ectopic lesions compared to eutopic endometrium and specifically in deep infiltrating endometriosis, indicating that LGR5 could be involved in progression and aggressiveness of the disease." (PMID 30577586, 2018). "Our previous findings show that LGR5+ cells from eutopic endometrium of women with DIE present a special subset of LGR5+ cells that could not only play a role in endometriosis in the eutopic endometrium, but also in the development of ectopic lesions and their aggressiveness." (PMID 30577586, 2018). "We did not observe significant differences in LGR5+ cells throughout the cycle in control or endometriosis groups, as similarly observed by other authors in normal, healthy endometrium." (PMID 30577586, 2018).
endometriosis (continued). "In the preliminary study, no variation in percentage of LGR5+ cells was observed throughout the menstrual cycle in nine eutopic endometriosis samples." (PMID 30577586, 2018). "However, comparison between ectopic lesions and eutopic endometrium in patients with endometriosis (ovarian and DIE) revealed a significant increase of LGR5+ cells in ectopic lesions." (PMID 30577586, 2018). "We performed immunofluorescence, flow cytometry, and primary culture in vitro experiments on eutopic and ectopic endometrium from healthy and endometriosis patients and observed that neither LGR5+ cells nor LGR5 expression varied throughout the cycle." (PMID 30577586, 2018). "In addition, no significant variation in LGR5 throughout the menstrual cycle was observed in control or endometriosis samples." (PMID 30577586, 2018). "Interestingly, we observed that LGR5+ cell percentage overexpressing CD163 (anti-inflammatory marker) was higher in healthy endometrium, suggesting that in endometriosis, endometrium presents a more pro-inflammatory phenotype that likely leads to poor obstetric outcomes." (PMID 30577586, 2018). "Interestingly, a non-significant decrease in LGR5 was observed in the proliferative phase of the treatment group in control samples, while we observed a non-significant increase in the secretory phase of endometriosis samples." (PMID 30577586, 2018). "LGR5 is aberrantly co-expressed with cytokeratin (CK) or E-cadherin (ECAD) in endometriotic eutopic endometrium, but this co-localization is not found in healthy women, suggesting that eutopic LCR5+ cells could have different behavior in endometriosis compared to healthy tissue." (PMID 30577586, 2018).
gastric adenocarcinoma (7 papers, 2016 to 2021). "Wound healing assay showed that LGR5 overexpression promoted mobility of gastric adenocarcinoma cells; whereas knockdown of LGR5 resulted in a significant decrease in cellular migration." (PMID 30089773, 2018). "We further explored the effect of LGR5-dependent Wnt/β-catenin-signaling pathway on gastric adenocarcinoma cell migration." (PMID 30089773, 2018). "To further examine the molecular mechanism by which LGR5 regulates gastric adenocarcinoma cell invasion, we examined the role of LGR5 in cytoskeleton organization." (PMID 30089773, 2018). "It appeared that overexpression of LGR5 had remarkable impact on the gastric adenocarcinoma cell growth." (PMID 30089773, 2018). "Collectively, this result suggests that LGR5 promotes cell proliferation, invasion and migration through Wnt/β-catenin-signaling pathway in gastric adenocarcinoma cells." (PMID 30089773, 2018). "We find that knock down of LGR5 or suppression of Wnt signaling pathway by inhibitor C59 arrests gastric adenocarcinoma cell proliferation and invasion." (PMID 30089773, 2018). "We observed that inactivation of the Wnt pathway led to a decrease in LGR5-induced proliferation and migration in gastric adenocarcinoma cells." (PMID 30089773, 2018). "Taken together, our results show that LGR5 contributes to cell proliferation and invasion through the activation of Wnt/β-catenin-signaling pathway in gastric adenocarcinoma cells." (PMID 30089773, 2018). "In the present study, we demonstrated that LGR5 increased cell proliferation, invasion, and migration using two different gastric adenocarcinoma cell lines SGC7901 and BGC823." (PMID 30089773, 2018). "Collectively, these data confirm the previous report demonstrating that activation of GLI2A in Lgr5+ gastric stem cells leads to the development of gastric adenocarcinoma." (PMID 30647844, 2018). "To investigate the biological significance of LGR5 in gastric adenocarcinomas, we used two gastric adenocarcinoma cell lines SGC7901 and BGC823." (PMID 30089773, 2018). "We performed colony formation assays and MTT assays with LGR5-overexpressed and knockdown in gastric adenocarcinoma cells." (PMID 30089773, 2018). "The present study demonstrated that LGR5 not only upregulates the expression of β-catenin, but also affects the subcellular localization of β-catenin in gastric adenocarcinoma cells." (PMID 30089773, 2018). "Here we show that GLI2A, an activator form of the Hh pathway transcription factor GLI2, drives rapid development of gastric adenocarcinomas from Lgr5-expressing gastric stem cells." (PMID 26859571, 2016). "Here, we show that LGR5 promotes gastric adenocarcinoma cell proliferation and metastasis." (PMID 30089773, 2018). "We observed that LGR5 induced the formation of vast number of lamellipodia and filopodia in gastric adenocarcinoma cells, corroborating its role in metastasis of gastric adenocarcinoma It was found that LGR5 indeed promoted formation of vast lamellipodia and filopodia as well as actin rearrangement." (PMID 30089773, 2018). "Moreover, treatment of Wnt3a, the activator of Wnt signaling pathway, partially recovers the proliferation defect observed in LGR5 knockdown gastric adenocarcinoma cells." (PMID 30089773, 2018). "Thus, our study elucidates the role of LGR5 in the context of cancer development especially in gastric adenocarcinoma." (PMID 30089773, 2018). "Here, we provided evidence that LGR5 promoted the proliferation, invasion, and migration of gastric adenocarcinoma through activation of Wnt/β-catenin-signaling pathway, which explains the underlying molecular mechanism of LGR5 overexpression during cancer development." (PMID 30089773, 2018). "Thus, our findings suggest that LGR5 facilitates the motility and invasiveness of gastric adenocarcinoma cells." (PMID 30089773, 2018).
gastric adenocarcinoma (continued). "To test the hypothesis, we assessed the actin remodeling of LGR5-overexpressing or knockdown gastric adenocarcinoma cells using actin staining (phalloidin) assay." (PMID 30089773, 2018). "We next evaluated the role of LGR5 in the invasion and migration of gastric adenocarcinoma cells." (PMID 30089773, 2018). "To investigate if LGR5 regulates the gastric adenocarcinoma cell proliferation through Wnt signaling, we used Wnt inhibitor or activator to regulate the Wnt pathway and detected the functional relationship between LGR5 and the Wnt/β-catenin pathway in BGC823 and SGC7901 cells." (PMID 30089773, 2018). "However, the oncogenic role of LGR5 in the development of gastric adenocarcinoma remains elusive." (PMID 30089773, 2018). "However, no detailed studies are available on LGR5 expression in poorly differentiated gastric adenocarcinoma (PD-AC)." (PMID 33676447, 2021).
ovarian tumors (7 papers, 2011 to 2024). "Here, using RNA in situ hybridization and/or immunohistochemistry, we thoroughly investigated LGR5 expression in normal human ovaries, fallopian tubes and various ovarian tumors." (PMID 35778589, 2022). "Therefore, this coupled epithelial-stromal expression of LGR5 in ovarian tumors might recapitulate the expression pattern observed during the early developmental stage." (PMID 35778589, 2022). "Ovarian tumors exhibit heterogeneity with distinct cell types expressing stem cell markers cluster of differentiation 133 (CD133), leucine-rich repeat-containing G-protein coupled receptor 5 (LGR5), aldehyde dehydrogenase 1 (ALDH1), and cytokeratin 6B (CK6B)." (PMID 38434767, 2024).
dysplasia (6 papers, 2017 to 2025). A usually neoplastic transformation of the cell, associated with altered architectural tissue patterns. "Expression of LGR5 in the normal was significantly lower compared to the tumor (p<0.0001), Barrett (p<0.0001), and dysplasia (p<0.0001) but tumor, Barrett, and dysplasia showed similar expression." (PMID 35154991, 2022). "In CACs, the distribution of LGR5 expression was heterogenous in the overlying mucosa and in some cases, overlying or adjacent dysplasia showed higher expression than the invasive component." (PMID 33541282, 2021). "Modelling the effects of fructose overconsumption on the BE-mouse model, we found that a HFrD accelerated the phenotypic progression of BE to dysplasia in correlation with reduced differentiation and enhanced Lgr5 stem cell expansion, especially in younger animals." (PMID 34946037, 2021). "Conversely, in the TZ of the gastroesophageal junction, Lgr5-expressing cells can transform into Lgr5-non-expressing progenitor cells that may develop into dysplasia and squamous cell carcinoma." (PMID 39684417, 2024).
oral squamous cell carcinoma (6 papers, 2019 to 2025). "The isoform of the stem cell marker LGR5, named LGR5Δ5 and first described by our group, is associated with prognosis and metastasis in oral squamous cell carcinoma (OSCC) and soft tissue sarcoma (STS)." (PMID 39769183, 2024). "A recent study found that only mRNA levels of splice variant LGR5Δ5 (LGR5 lacking exon 5), but not full-length LGR5 was significantly associated with poor prognosis in oral squamous cell carcinoma." (PMID 39821694, 2025). "Lgr5 expression also increases with disease severity in human oral squamous cell carcinoma, although the data were not stratified based on HPV status of the lesions." (PMID 36016373, 2022).
papilloma (6 papers, 2011 to 2022). A benign epithelial neoplasm that projects above the surrounding epithelial surface and consists of villous or arborescent outgrowths of fibrovascular stroma. "We used this virus to discern the contributions made by Lgr5+ cells in the development of squamous dysplasia/papillomas and associated squamous cell carcinomas (SCCs) in mouse skin." (PMID 36016373, 2022). "To verify the contribution of Lgr5+ cells (with Pten loss) in papilloma and SCC, we performed IF staining of tissue sections of these tumors derived from Lgr5-Pten-/- mice and Lgr5-Pten+/+ mice for the expression of Lgr5, and we did not detect the presence of Lgr5-expressing cells." (PMID 31754399, 2019). "We conclude that gene copy number changes, somatic mutations, and alterations in tissue composition in papillomas and carcinomas account for the loss of the Ccnd1, Hras1, and Lgr5 eQTL and likely are responsible for the loss of many other eQTL seen in normal skin." (PMID 21244661, 2011). "Although 6 out of 14 mice succumbed to adrenal tumours, 50% of these mice presented with papillomas consistent with LGR5 expression in murine skin." (PMID 27558455, 2016). "A number of genes related to cancer stem cells were validated by qRT-PCR, including Cxcl12/Sdf-1, Pdgfra, Lgr5, Lrg1, Pecam1/CD31, H19 and Src2, which were all significantly upregulated in Nanog-papillomas and Nanog-SCCs relative to control papillomas." (PMID 25988972, 2015). "Although Lgr5 is significantly expressed in papillomas and carcinomas, it is not under the control of a cis-eQTL in tumors, and also is not linked genetically to the hair follicle correlation network." (PMID 21244661, 2011). "Moreover, the average number of papillomata per mouse in Lgr5-Pten-/--TNF-/-mice was much lower compared to that in Lgr5-Pten-/- mice, and TNF-/- mice did not develop papilloma when receiving the same DMBA /TPA treatment." (PMID 31754399, 2019).
brain cancer (5 papers, 2014 to 2025). A primary or metastatic malignant neoplasm affecting the brain. "High LGR5 protein expression has also been associated with poor outcome and recurrence in cancers of the brain, lung, esophagus, breast, colon, cervix and ovary." (PMID 39821694, 2025). "Consistent with a previous study, which showed that LGR5 knockdown suppresses viability and induces apoptosis of brain cancer stem cells, our data revealed that LGR5 knockdown inhibited tumorsphere formation." (PMID 24172981, 2014). "Leucine-rich repeat containing G protein-coupled receptor 5 (LGR5), one of the target genes of the Wnt signaling pathway, has recently been identified as a marker for brain cancer stem-like cells." (PMID 24172981, 2014).
Ewing sarcoma (5 papers, 2013 to 2019). A small round cell tumor that lacks morphologic, immunohistochemical, and electron microscopic evidence of neuroectodermal differentiation. "It has been reported that LGR5 regulates Wnt/β-catenin signaling by associating with R-spondin and enhances cell proliferation in intestinal epithelium and Ewing sarcoma." (PMID 25193857, 2014). "Indeed, LGR5 is highly expressed in aggressive Ewing sarcoma and CSCs and the binding of RSPO-2 on LGR5 was able to potentiate Wnt3a-induced canonical Wnt signaling." (PMID 31370265, 2019). "However, it seems that an important variability in Wnt responsiveness exists among Ewing sarcoma cells based on the differential expression of LGR5 and the availability of Wnt and RSPO ligands in the tumor microenvironment." (PMID 31370265, 2019). "Recently, LGR5 was found to potentiate Wnt/β-catenin signaling in HEK293T cells and in Ewing sarcoma, and LGR5 was found to function as a receptor of R-spondins to enhance Wnt-induced LRP phosphorylation and then activate Wnt/β-catenin signaling." (PMID 25193857, 2014).
invasive carcinoma (5 papers, 2011 to 2022). A carcinoma that is not confined to the epithelium, and has spread to the surrounding stroma. "In particular, LGR5 expression declines throughout the progression from STIC to invasive carcinoma and is significantly associated with improved PFS in HGSC patients." (PMID 35778589, 2022). "Next we tested the hypothesis that the sequential changes of gastric carcinogenesis, i.e. chronic atrophic gastritis, intestinal metaplasia and invasive carcinoma, are associated with a reallocation of the LGR5+ cells." (PMID 22530031, 2012). "Histologically, LGR5 expression was only observed in invasive carcinomas of no special type." (PMID 34493772, 2021).